FILIP1L (filamin A interacting protein 1 like)
Description:
Acts as a regulator of the antiangiogenic activity on endothelial cells. When overexpressed in endothelial cells, leads to inhibition of cell proliferation and migration and an increase in apoptosis. Inhibits melanoma growth When expressed in tumor-associated vasculature.
Synonyms: DOC-1; DOC1; GIP90; GIP130
Tractability: Antibody: the Human Protein Atlas places it where antibodies can reach. PROTAC: ubiquitination databases record sites on it; its protein half-life has been measured.
Gene: Protein-coding gene on chromosome 3 (99,828,811 to 100,114,513, reverse strand). Ensembl gene ENSG00000168386.
Subcellular location: Cytoplasm; Membrane; Nucleus
Subcellular location (Human Protein Atlas): Plasma membrane
Gene Ontology:
Biological process: protein localization to actin cytoskeleton
Cellular component: actin cytoskeleton; cytoplasm; membrane; nucleus
Genetic constraint (gnomAD): Loss-of-function variants: 55 observed, 100.45 expected, observed/expected ratio (o/e) 0.55, 90% interval 0.44 to 0.69. The upper end of that interval is the gene's LOEUF score, 0.69, which puts it in group 2 of 6, group 1 being the genes least tolerant of losing a copy. Missense variants: 1,272 observed, 1,382 expected, observed/expected ratio (o/e) 0.92, 90% interval 0.88 to 0.96. Synonymous variants: 444 observed, 496.51 expected, observed/expected ratio (o/e) 0.89, 90% interval 0.83 to 0.97.
Homologues: Orthologues: chimpanzee FILIP1L (99% identical), macaque FILIP1L (98% identical), rabbit FILIP1L (93% identical), pig FILIP1L (91% identical), dog FILIP1L (88% identical), rat Filip1l (86% identical), guinea pig FILIP1L (85% identical), mouse Filip1l (84% identical), tropical clawed frog filip1l (64% identical), Caenorhabditis elegans C49H3.6 (10% identical). Paralogues in human: FILIP1 (45% identical), LUZP1 (18% identical), CTTNBP2NL (12% identical).
Diseases named in the same sentence as FILIP1L in open-access papers:
FILIP1L is named in the same sentence as 33 diseases in open-access papers, as found by Europe PMC text mining. Sharing a sentence is not in itself a finding about the gene and the disease. The quoted sentences say what the papers report.
ovarian carcinoma (9 papers, 2012 to 2024). A malignant neoplasm originating from the surface ovarian epithelium. "We previously demonstrated that the down-regulation of FILIP1L expression associated with DNA methylation in the FILIP1L promoter is related with invasive potential in ovarian cancer cell lines." (PMID 24340050, 2013). "FILIP1L was shown to be one of nine genes associated with functional suppression of tumorigenicity in ovarian cancer cell lines." (PMID 24340050, 2013). "Down-regulation of FILIP1L in ovarian cancer has recently been linked to promoter methylation, although alternate modes of expression control likely also exist." (PMID 22900064, 2012). "It is also noteworthy that in ovarian, prostate and pancreatic cancer, FILIP1L expression is silenced by DNA hypermethylation; this has been linked to aggressiveness and metastatic potential, and is even considered an independent prognostic marker in ovarian cancer [47,]." (PMID 34000624, 2021). "Filamin A interacting protein 1-llike (FILIP1L) is a novel tumor suppressor-like protein which has its expression downregulated in various cancers, like colorectal cancer, ovarian cancer, and lung cancer." (PMID 39682415, 2024). "A recent study has shown that reduced expression of FILIP1L in ovarian cancer is related to the invasive phenotype." (PMID 29100323, 2017). "As anti-angiogenic strategy such as anti-VEGF therapy is another potential treatment in ovarian cancer, it potentiates the possibility of FILIP1L being a therapeutic target in ovarian cancer." (PMID 27776341, 2016). "These morphological changes were reverted by simultaneous knockdown of FILIP1L and SLUG, supporting the notion that FILIP1L exerts its anti-tumor activity by suppressing SLUG-mediated EMT in ovarian cancer cells." (PMID 27776341, 2016). "FILIP1L knockdown induced chemoresistance in ovarian cancer cells and this phenotype was rescued by simultaneous knockdown of FILIP1L and SLUG, an EMT activator." (PMID 27776341, 2016). "In this study, we show that FILIP1L is a marker of prognosis, stage and chemosensitivity in ovarian cancer." (PMID 27776341, 2016). "Induction of SLUG was consistently inhibited by FILIP1L following WNT signaling activation in several ovarian cancer cell lines tested." (PMID 27776341, 2016). "As shown in the present study, the tumor suppressor FILIP1L is down-regulated in metastatic and chemoresistant ovarian cancer patient samples." (PMID 27776341, 2016). "In the present study, we demonstrated that FILIP1L expression was inversely correlated with poor prognosis, stage and chemoresistance in ovarian cancer." (PMID 27776341, 2016). "FILIP1L down-regulation was confirmed by cDNA microarray analysis in ovarian carcinoma cells from patients with late-stage disease." (PMID 24340050, 2013). "We previously identified Filamin A interacting protein 1-like (FILIP1L) as an important inhibitor of cell migration and invasion in ovarian cancer." (PMID 24340050, 2013). "As in ovarian cancer, DNA methylation is a mechanism by which FILIP1L is down-regulated in these cancer histologies." (PMID 24340050, 2013). "We identified Filamin A interacting protein 1-like (FILIP1L; previously known as down-regulated in ovarian cancer 1 [DOC1]) as an important inhibitor of cell migration and invasion." (PMID 24340050, 2013). "We previously demonstrated that FILIP1L expression was inversely correlated with the invasive potential of ovarian cancer cell lines and ovarian cancer specimens." (PMID 24340050, 2013). "Differential gene expression analysis revealed that the FILIP1L gene in ovarian cancer cells presents several tagging single nucleotide polymorphisms." (PMID 24340050, 2013). "We also demonstrated that DNA methylation in the FILIP1L promoter was a mechanism by which FILIP1L was down-regulated in ovarian cancer." (PMID 24340050, 2013). "The FILIP1L gene was originally identified as a gene down-regulated in ovarian cancer, or DOC1, compared to normal ovarian epithelial cells." (PMID 22900064, 2012).
ovarian carcinoma (continued). "Moreover, filamin A-interacting protein 1-like (FILIP1L), a key mediator of doxorubicin-induced apoptosis, was downregulated in ovarian cancer cell lines and clinical specimens, and negatively correlated with their invasive potential." (PMID 31681605, 2019). "A recent study had shown that down-regulated expression of FILIP1L is related to the invasive phenotype in ovarian tumor, indicating that FILIP1L has the potential to be a biomarker for invasive potential and a target for novel ovarian cancer therapy." (PMID 29100323, 2017). "Our study provides the first clinical relevance of FILIP1L in human cancer, and suggests that FILIP1L may be a novel prognostic marker for chemotherapy in ovarian cancer patients." (PMID 27776341, 2016). "FILIP1L knockdown induces chemoresistance in ovarian cancer cells." (PMID 27776341, 2016). "Further characterization of the mechanism of action of FILIP1L on chemosensitivity may help elucidate the role played by FILIP1L in ovarian cancer recurrence and result in the development of more effective treatment regimens." (PMID 27776341, 2016). "Our clinical and cellular data indicating potential associations between FILIP1L and SLUG led us to hypothesize that FILIP1L blocks EMT in ovarian cancer by virtue of decreasing the pool of active β-catenin." (PMID 27776341, 2016). "The results we have presented suggest that the utility of determining FILIP1L expression in patients' samples could provide important prognostic information as high levels correlate with a good prognosis and lower probability of recurrence in ovarian cancer." (PMID 27776341, 2016). "To study the clinical implications of FILIP1L in regulating the WNT/β-catenin pathway and chemoresistance, we examined the expression of FILIP1L, β-catenin, SNAIL and SLUG in ovarian cancer specimens from patients in whom clinical outcome data were available." (PMID 27776341, 2016). "To this end, we decreased FILIP1L and SLUG expression in two ovarian cancer cell lines from high-grade serous carcinoma, the relevant histosubtype for chemoresistance using siRNA transfection." (PMID 27776341, 2016). "FILIP1L expression was correlated negatively with the expression of β-catenin and SLUG, whereas β-catenin expression was correlated positively with SLUG expression, suggesting a link between FILIP1L and the WNT/β-catenin pathway in ovarian cancer." (PMID 27776341, 2016). "FILIP1L mRNA was originally characterized by its presence in human ovarian surface epithelial (HOSE) cells and its absence in ovarian carcinoma cells." (PMID 24340050, 2013). "FILIP1L was first discovered to be expressed in human normal ovarian epithelial cells, but invariably nonexistent in ovarian cancer cell lines." (PMID 29100323, 2017). "Moreover, the tumor-suppressor activity of FILIP1L is exerted through its inhibition of EMT, a mechanism of metastasis and chemoresistance in ovarian cancer." (PMID 27776341, 2016). "Two ovarian cancer cell lines, OVCA429 and SKOV3, were engineered to express FILIP1L at levels within the same order of magnitude as those in immortalized normal ovarian epithelial cells as shown by both mRNA and protein expression, as well as expressing near-infrared fluorescent protein 720 (iRFP)." (PMID 27776341, 2016). "In addition, the expression of FILIP1L was negatively correlated with the expression of SLUG in clinical samples, suggesting a link between FILIP1L and the SLUG-mediated EMT pathway in ovarian cancer." (PMID 27776341, 2016). "FILIP1L facilitates β-catenin degradation, thereby down-regulating EMT in ovarian cancer cells." (PMID 27776341, 2016). "We noted that treating ovarian cancer cell lines with a histone deacetylase inhibitor did not change FILIP1L mRNA and protein levels in these cell lines, leading us to conclude that histone acetylation was not a major epigenetic regulator of FILIP1L." (PMID 27776341, 2016).
ovarian carcinoma (continued). "We speculate that FILIP1L may exert its tumor-suppressor activity by degrading increased β-catenin regardless of ovarian cancer subtype." (PMID 27776341, 2016). "Although master EMT-regulating transcription factors SLUG and SNAIL were shown to be directly associated with cisplatin and paclitaxel resistance in ovarian cancer, SLUG but not SNAIL was consistently modulated by FILIP1L in our in vitro, in vivo and clinical specimen data." (PMID 27776341, 2016). "Having shown in clinical samples that FILIP1L expression decreases with tumor progression, we tested whether or not re-expression of FILIP1L could inhibit ovarian cancer metastases in an orthotopic mouse model." (PMID 27776341, 2016).
breast carcinoma (4 papers, 2013 to 2026). "This study confirms the role of m6A-SNPs in influencing endocrine therapy resistance in ER+ breast cancer, highlighting how modifications mediated by specific SNPs, particularly in FILIP1L and TOM1L1, impact key regulatory pathways and cellular metabolism." (PMID 40303916, 2025). "Moreover, the upregulated FILIP1L was also able to increase the sensitivity of breast cancer cells to Topoisomerase II (TOP2) targeting drugs." (PMID 40303916, 2025). "Interestingly, histone deacetylase inhibitor Trichostatin A (TSA) treatment also resulted in significantly increased FILIP1L mRNA expression in these cancer cell lines, except for the BT-549 breast cancer cell line." (PMID 24340050, 2013). "FILIP1L expression increases with EMT progression and correlates with poor outcomes in breast cancer patients." (PMID 42040966, 2026). "In ER+ breast cancer, the modulation of the PI3K-Akt and Wnt signaling pathways by m6A-SNPs related genes like FILIP1L and TOM1L1 is particularly compelling, given the established role of these pathways in promoting estrogen receptor signaling and cellular proliferation." (PMID 40303916, 2025). "Interestingly, breast cancer cell line MCF7, which has been shown to be a non-invasive cell line, demonstrated as high FILIP1L expression as normal breast epithelial cells HMEC." (PMID 24340050, 2013).
colon cancer (4 papers, 2012 to 2022). "Downregulation of FILIP1L is associated with chemoresistance and poor prognosis in ovarian and colon cancer." (PMID 36860703, 2022). "While the mutation frequency for the FILIP1L gene was not significant in our study, CortBP2 ranked in the top 75 domains with the highest mutation frequency, suggesting a novel role in colon cancer development for FILIP1L and the other genes containing mutations in the CortBP2 domain." (PMID 22759657, 2012). "FILIP1L regulates proteasome-dependent degradation of PFDN1, and increased PFDN1, caused by downregulation of FILIP1L, drives mucin secretion in colon cancer." (PMID 36860703, 2022). "We have recently shown that FILIP1L regulates proteasome-dependent degradation of the molecular chaperone PFDN1, and that increased PFDN1 expression, resulting from downregulation of FILIP1L leads to cytokinesis defects and enhanced tumor growth in colon cancer." (PMID 36860703, 2022).
colorectal cancer (4 papers, 2016 to 2024). A primary or metastatic malignant neoplasm that affects the colon or rectum. "We also evaluated FILIP1L expression in colorectal cancer patient samples and examined associations between FILIP1L expression and patient prognoses." (PMID 27750216, 2016). "To determine the prognostic value of FILIP1L in human colorectal cancer, we examined associations between FILIP1L levels in formalin-fixed, paraffin-embedded tissue sections obtained from 354 colorectal cancer patients and clinicopathological data." (PMID 27750216, 2016). "To evaluate whether FILIP1L affects growth and metastasis in colorectal cancer, we examined FILIP1L expression in human colorectal cancer tissues and its association with clinicopathological features, including overall survival." (PMID 27750216, 2016). "Finally, we evaluated associations between FILIP1L expression and human colorectal cancer cell apoptosis, proliferation, and angiogenesis to confirm our in vitro results." (PMID 27750216, 2016). "FILIP1L expression, which was lower in colorectal cancer tissues than in normal colorectal mucosa, was associated with reductions in tumor size, cell differentiation, lymphovascular invasion, cancer stage, invasion depth, and lymph node metastasis, and with longer overall survival." (PMID 27750216, 2016). "Taken together, our results indicate that FILIP1L inhibits progression in colorectal cancer by inhibiting tumor cell proliferation and angiogenesis." (PMID 27750216, 2016). "Immunohistochemical FILIP1L protein staining was primarily cytoplasmic in normal and colorectal cancer cells." (PMID 27750216, 2016). "In this study, we evaluated the effects of FILIP1L on oncogenic behavior and prognosis in colorectal cancer." (PMID 27750216, 2016). "FILIP1L protein levels were examined by Western blotting in various human colorectal cancer cell lines, including SW480, DLD1, DKO1, HCT116, HT29, and COLO205 cells." (PMID 27750216, 2016). "Furthermore, a third related protein, FILIP1L, also inhibits tumor cell migration and invasion in colorectal cancer models." (PMID 33869174, 2021). "To examine whether FILIP1L activates oncogenic signaling pathways in human colorectal cancer cells, we measured phosphorylated β-catenin, Akt, and GSK-3β protein levels, using Western blotting." (PMID 27750216, 2016). "In addition, FILIP1L mRNA and protein levels are down-regulated in various human cancers, including ovarian, prostate, breast, lung, pancreatic, and colorectal cancers." (PMID 27750216, 2016). "Next, we examined whether FILIP1L affects the activation of intracellular signaling pathways involved in oncogenic processes, including apoptosis, proliferation, and angiogenesis, in colorectal cancer cells." (PMID 27750216, 2016). "Although FILIP1L may be a promising molecular target for cancer treatment, whether FILIP1L suppresses tumor progression in colorectal cancer remains unknown." (PMID 27750216, 2016).
lung adenocarcinoma (4 papers, 2022 to 2024). A carcinoma that arises from the lung and is characterized by the presence of malignant glandular epithelial cells. "In lung adenocarcinoma, smoking induces the downregulation of filamin A interacting protein 1-like (FILIP1L), which activates the Wnt/β-catenin signaling pathway, resulting in mucin secretion, inflammation, and fibrosis." (PMID 39534084, 2024). "In human lung tissue, smoking has been demonstrated to downregulate FILIP1L, which can drive lung adenocarcinoma." (PMID 38199042, 2024). "Findings presented herein suggest that downregulation of FILIP1L is a clinically relevant event in the pathogenesis and clinical course of lung adenocarcinomas (LUAD)." (PMID 36860703, 2022).
prostate carcinoma (3 papers, 2013 to 2021). A carcinoma that arises from epithelial cells of the prostate gland. "Methylation inactivation of tumor suppressor gene FILIP1L was important for pathogenesis of prostate cancer, but loss of this gene may be associated with the development of GBM." (PMID 31137733, 2019). "Others have shown that FILIP1L expression was down-regulated in prostate cancers compared with normal tissues." (PMID 24340050, 2013). "To date, FILIP1L has been shown to be down-regulated only in ovarian and prostate cancers among human cancer histologies." (PMID 24340050, 2013). "Recently, we and others have demonstrated that DNA methylation in the FILIP1L promoter was the mechanism by which FILIP1L was down-regulated in ovarian and prostate cancers." (PMID 24340050, 2013). "In addition, since FILIP1L promoter methylation was associated with FILIP1L down-regulation in ovarian and prostate cancers, we examined whether or not the same mechanism is responsible for the down-regulation of FILIP1L in other cancer histologies." (PMID 24340050, 2013).
cutaneous squamous cell carcinoma (2 papers, 2021 to 2022). "Promoter methylation-associated FILIP1L downregulation was also implicated in human cancer tissues such as ovarian, prostate, and cutaneous squamous cell carcinoma." (PMID 36860703, 2022).
lung carcinoma (2 papers, 2022 to 2024). "As such, we used a public database to more comprehensively examine the association of FILIP1L mRNA expression and FILIP1L promoter DNA methylation in a panel of lung cancer lines." (PMID 36860703, 2022). "From the 23 lung cancer databases in the cBioPortal search, the somatic mutation frequency for FILIP1L gene is only 0.9% and the majority are missense mutations." (PMID 36860703, 2022). "Preliminary immunoblot experiments demonstrated that FILIP1L expression coincided inversely with PFDN1 protein levels in lung cancer cell lines." (PMID 36860703, 2022). "We first asked whether FILIP1L knockdown leads to cytokinesis defects in lung cancer cells." (PMID 36860703, 2022). "Thus, we examined the relationships between FILIP1L and PFDN1 expression in the context of lung cancer." (PMID 36860703, 2022). "FILIP1L knockdown and the resultant PFDN1 increase lead to increased mucin secretion and/or overexpression in mouse lung as well as lung cancer cells, possibly generating a niche for lung cancer progression through increased inflammation and fibrosis." (PMID 36860703, 2022).
metastatic carcinoma (2 papers, 2016 to 2021). A carcinoma which has spread from the original site of growth to another anatomic site. "Doxycycline-inducible FILIP1L+ clones from an ES2 cell line also resulted in a significant reduction in peritoneal metastases, compared to the control demonstrating metastatic cancer spread into the peritoneum and the surface of visceral organs and the diaphragm." (PMID 27776341, 2016).